Y_RNA (Y RNA )
Gene: Miscellaneous RNA gene on chromosome 5 (98,936,638 to 98,936,747, reverse strand). Ensembl gene ENSG00000200351.
Homologues: Orthologues: chimpanzee Y_RNA (99% identical), macaque Y_RNA (95% identical). Paralogues in human: RNY1 (90% identical), RNY1P11 (88% identical), Y_RNA (88% identical), Y_RNA (87% identical), Y_RNA (86% identical), Y_RNA (85% identical), RNY1P8 (85% identical), Y_RNA (84% identical), RNY1P10 (83% identical), RNY1P5 (83% identical), Y_RNA (83% identical), RNY1P15 (82% identical), and 99 more.